CSF2RB (colony stimulating factor 2 receptor subunit beta)
Diseases named in the same sentence as CSF2RB in open-access papers (continued):
Sharing a sentence is not in itself a finding about the gene and the disease.
colitis (3 papers, 2015 to 2025). Inflammation of the colon. "We then subjected our wt mice to 2% DSS in the drinking water for 7 days to establish murine colitis and found that Csf2rb mRNA expression was significantly elevated in the distal part of the colon comparing to mice receiving normal drinking water." (PMID 40586774, 2025). "In order to find out the role of CD131 in DSS-induced murine colitis, we subjected CD131-deficient mice (Csf2rb+/–) to DSS administration and compared them to control wt mice." (PMID 40586774, 2025). "This alteration in the composition of the cellular infiltrate correlated with a significantly reduced colitis score in Csf2rb−/− compared to WT mice and a decrease in the ratio of activated to resting eosinophils in the intestine." (PMID 26200014, 2015). "Because the lack of colitis observed in Csf2rb−/− mice correlated with a decrease in the frequency of eosinophils, but not neutrophils, we next investigated the relative contribution of these distinct innate effectors to the pathogenesis of colitis." (PMID 26200014, 2015). "Lack of a GM-CSF-Rβ signal in Csf2rb−/− mice reduced EoP and eosinophil increases in the BM in this chronic model of colitis." (PMID 26200014, 2015).
COVID-19 (3 papers, 2020 to 2021). A disease caused by infection with severe acute respiratory syndrome coronavirus 2. "We found CFSF2RA downregulated and CSF2RB upregulated in the lung of the COVID-19-affected patient." (PMID 33173052, 2020).
depression (3 papers, 2012 to 2023). "A possible correlation between these cytokines and depression has been postulated on the basis of the increased genetic risk for major depression associated with the colony stimulating factor 2 receptor β (CSF2RB) haplotype, which encodes a protein in high affinity receptors binding IL-5." (PMID 23046564, 2012).
experimental autoimmune encephalomyelitis (3 papers, 2016 to 2021). An autoimmune demyelinating disease of the central nervous system that is produced experimentally in animals by the injection of homogenized brain or spinal cord in Freund's adjuvant. "In an animal model of multiple sclerosis (experimental autoimmune encephalomyelitis), conditional deletion of Csf2rb (the mouse ortholog of CD131) in CCR2+ monocytes abrogates a pathogenetic signature that is required for disease development." (PMID 28138327, 2016).
lung adenocarcinoma (3 papers, 2022 to 2025). A carcinoma that arises from the lung and is characterized by the presence of malignant glandular epithelial cells. "Higher CSF2RB expression in lung adenocarcinoma tumors is associated with better survival, in line with our observations in peripheral blood." (PMID 36303210, 2022). "The expression of CSF2RB in lung adenocarcinoma was lower in the tumor sample than in the normal sample, and low expression was related to poor survival." (PMID 40837403, 2025). "We used LIMMA package to compare the expression differences of CCR2 and CSF2RB in lung adenocarcinoma tumor tissues and normal tissues." (PMID 35574409, 2022). "To confirm the expression of CSF2RB in lung adenocarcinoma cells, we collected lung adenocarcinoma tissues and para-cancerous tissues from the Tianjin Cancer Hospital and Institute." (PMID 35574409, 2022). "We found that the expression of CSF2RB mRNA in lung adenocarcinoma tissues was significantly lower than in adjacent tissues." (PMID 35574409, 2022). "To further verify this finding, we detected CSF2RB protein expression in 20 pairs of matched lung adenocarcinoma and tumor-adjacent tissues by using immunohistochemistry." (PMID 35574409, 2022). "CSF2RB effectively predicted the prognosis of patients with lung adenocarcinoma which could also be a potential target for cancer treatment and prevention." (PMID 35574409, 2022). "Moreover, the low expression of CSF2RB was closely related to the late clinical pathological stages and poor prognosis of lung adenocarcinoma patients, which enabled CSF2RB to serve as an independent prognostic factor." (PMID 35574409, 2022). "Furthermore, CSF2RB correlated with immune infiltrates in lung adenocarcinoma." (PMID 35574409, 2022). "In our study, we found that CSF2RB is an important biomarker in LUAD, which may act as a tumor-suppressor gene to inhibit the growth, proliferation, and differentiation of lung adenocarcinoma." (PMID 35574409, 2022).
atherosclerosis (2 papers, 2020 to 2021). A disease characterized by the build-up of fatty material and calcium deposition in the arterial wall resulting in partial or complete occlusion of the arterial lumen. "Our study also found that new genes like CSF2RB, IL1RN, CCL5, MMP9, CD53, NCF2 and TLR2 associated with Inflammation present high expression both in psoriasis and atherosclerosis." (PMID 34122426, 2021).
autoimmune disease (2 papers, 2014 to 2022). A disorder resulting from loss of function or tissue destruction of an organ or multiple organs, arising from humoral or cellular immune responses of the individual to their own tissue constituents. "One of the ligands of CSF2RB (that is, GM-CSF) has long been implicated in the pathogenesis of RA, and other rheumatic or autoimmune diseases." (PMID 24690414, 2014). "Interestingly, FOXP3+ regulatory T cells (Tregs), which play a pivotal role in prevention of autoimmunity have been demonstrated to highly overexpress CSF2RB and genome-wide association studies (GWAS) identified CSF2RB as being linked to autoimmune diseases like multiple sclerosis (MS)." (PMID 36532080, 2022). "Thus, further studies are necessary to fully characterize any potential role CSF2RB might exert in Treg stability and function and its role in autoimmune disorders." (PMID 36532080, 2022).
autoimmune disorders (2 papers, 2019 to 2022). "Further, guided by previous genetic and transcriptomic studies, we demonstrate an association between CSF2RB expression in Tregs and autoimmunity." (PMID 36532080, 2022). "Thus, since CSF2RB is linked to autoimmunity and inflammation and highly expressed by human Tregs, we here investigated the potential role of CSF2RB in human Tregs in detail." (PMID 36532080, 2022). "To determine whether CSF2RB expression of Tregs relates to autoimmunity, we re-analyzed published transcriptomic datasets of Tregs isolated from healthy controls and patients with MS, rheumatoid arthritis (RA) and SLE." (PMID 36532080, 2022).
cervical squamous cell carcinoma (2 papers, 2020 to 2025). A squamous cell carcinoma arising from the cervical epithelium. "CSF2RB is the common beta chain receptor for the GM-CSF, IL-3, and IL-5 activation and a rare genetic variant of CSF2RB (rs16997517) is related to a decreased risk of squamous cell cervical cancer." (PMID 33042828, 2020).
Crohn disease (2 papers, 2022 to 2025). A gastrointestinal disorder characterized by chronic inflammation involving all layers of the intestinal wall, noncaseating granulomas affecting the intestinal wall and regional lymph nodes, and transmural fibrosis. "In support of this, a genetic analysis of Ashkenazi Jewish populations, which show a high prevalence of Crohn’s disease, demonstrates that monocytes from carriers of a frameshift mutation in CSF2RB gene exhibit reduced responses to GM-CSF treatment." (PMID 40586774, 2025). "Besides, in a genetic analysis of Ashkenazi Jewish populations that have a high prevalence of Crohn’s disease, a frameshift mutation in CSF2RB gene (encoding CD131) was shown associated with higher risk for Crohn’s disease and reduced monocyte signaling in response to GM-CSF." (PMID 40586774, 2025).
influenza (2 papers, 2014 to 2020). An acute viral infection of the respiratory tract, occurring in isolated cases, in epidemics, or in pandemics; it is caused by serologically different strains of viruses (influenzaviruses) designated A, B, and C, has a 3-day incubation period, and usually lasts for 3 to 10 days. "Presence of wild-type AM in Csf2rb−/− mice protected from pulmonary proteinosis, severe morbidity and mortality following influenza infection." (PMID 24699679, 2014).
lung fibrosis (2 papers, 2014 to 2021). "The variants involved two genes associated with surfactant metabolism dysfunction (ABCA3 and CSF2RB), two with pulmonary fibrosis (MUC5B and SFTP), one with bronchiectasis (SCNN1B), and one with alpha-1-antitrypsin deficiency (SERPINA1)." (PMID 33526882, 2021). "In the adult with a CSF2RB mutation, thoracic CT scans showed the progressive appearance of traction bronchiectasis and cystic lesions suggestive of fibrosis, but no lung fibrosis was described in children bearing CSF2RA mutations." (PMID 24927752, 2014).
neuroblastoma (2 papers, 2020 to 2022). Neuroblastoma (NB) is the most common solid, extracranial childhood tumor. "Runt-related transcription factor 1 directly bound to the promoters of CSF2RB, which regulated apoptosis of neuroblastoma." (PMID 33553270, 2020).
triple-negative breast carcinoma (2 papers, 2022 to 2025). An invasive breast carcinoma which is negative for expression of estrogen receptor (ER), progesterone receptor (PR), and human epidermal growth factor receptor 2 (HER2). "CSF2RB was discovered to be connected with clinical characteristics of triple-negative breast cancer using the WGCNA as an immune-related hub gene." (PMID 36276869, 2022). "CSF2RB expression is downregulated in luminal and HER2-positive samples but upregulated in triple-negative breast cancer (TNBC), compared to that in normal samples." (PMID 40837403, 2025). "Together, these results indicate that the CSF2RB gene potentially plays i) a protective or tumor-suppressive role in luminal and HER2+ subtypes and ii) an oncogenic role in triple-negative breast cancers (TNBC)." (PMID 40837403, 2025).
viral infection (2 papers, 2017 to 2022). "A previous study investigating another in vitro transforming CSF2RB mutation found that the transformation rate of infected cells increased with the time in culture after viral infection and before factor withdrawal." (PMID 28208123, 2017). "Expression of the βc receptor transcript (CSF2RB) was significantly increased at both day 3 and day 6 post IAV infection, consistent with persistent tissue infiltration of βc receptor-expressing inflammatory cells during acute viral infection." (PMID 35145069, 2022).
Alzheimer disease (1 paper, 2020). A progressive, neurodegenerative disease characterized by loss of function and death of nerve cells in several areas of the brain leading to loss of cognitive function such as memory and language. "Moreover, CSF2RB was found overexpressed on monocytes from Alzheimer's disease patients, which contributed to granulocyte-macrophage colony-stimulating factor-induced monocyte migration." (PMID 33553270, 2020).
breast invasive carcinoma (1 paper, 2025). "We analyzed the CSF2RB promoter methylation level in breast invasive carcinoma samples from TCGA and among the major subclasses based on the patient’s race and the pathological stage of breast invasive carcinoma per TCGA sample." (PMID 40837403, 2025). "We estimated the effect of CSF2RB expression on breast invasive carcinoma survival probability." (PMID 40837403, 2025). "We analyzed the CSF2RB transcript expression per breast invasive carcinoma subclass, performed a pan-cancer analysis of CSF2RB expression across normal and tumor samples of TCGA cancer samples, and analyzed CSF2RB expression across TCGA tumor samples using UALCAN." (PMID 40837403, 2025).
cervical cancer (1 paper, 2025). A primary or metastatic malignant neoplasm involving the cervix. "To investigate the biological relevance of genes within the NAGS model, we first analyzed the expression levels of CSF2RB, SEMA6B, and IRF4 in the TCGA cervical cancer dataset." (PMID 40564066, 2025).
gout (1 paper, 2022). A condition characterized by painful swelling of the joints, which is caused by deposition of urate crystals. "The results of RT-qPCR showed that the expressions of CCL7, CSF2RB and IL-1β were significantly up-regulated in the gout group compared with the control group (p < 0.05)." (PMID 36313318, 2022).
hereditary pulmonary alveolar proteinosis (1 paper, 2025). "Hereditary pulmonary alveolar proteinosis (hPAP) is a rare disorder caused by mutations in the CSF2RA or CSF2RB genes, leading to impaired surfactant clearance by alveolar macrophages and subsequent respiratory dysfunction." (PMID 40486150, 2025).
Hodgkins lymphoma (1 paper, 2023). A heterogeneous group of malignant lymphoid neoplasms of B-cell origin characterized histologically by the presence of Hodgkin and Reed-Sternberg (HRS) cells in the vast majority of cases. "CSF2RB has been shown to be recurrently mutated in Hodgkin lymphoma cell lines and Hodgkin lymphoma primary samples." (PMID 37910143, 2023).
Hyperglycemia (1 paper, 2023). An increased concentration of glucose in the blood. "Our combined method of ATAC and RNA sequencing revealed Csf2rb, Btla, and Isg15 as the key candidate genes associated with hyperglycemia, azotemia, and albuminuria." (PMID 38022502, 2023).
injury (1 paper, 2015). Damage inflicted on the body as the direct or indirect result of an external force, with or without disruption of structural continuity. "Notably, complement activation is associated with various organ injuries, including acetaminophen-induced liver injury, and CSF2RB is a high-affinity receptor for IL-3, IL-5, and colony-stimulating factor." (PMID 26335687, 2015).
myocardial infarction (1 paper, 2023). Gross necrosis of the myocardium, as a result of interruption of the blood supply to the area, as in coronary thrombosis. "For example, colony-stimulating factor 2 (CSF2) is a signaling chemokine that along with its cognate receptor pair CSF2RB modulates leukocyte production and proliferation as well as MSC recruitment and post-myocardial infarction (MI) cardiac remodeling." (PMID 37600026, 2023).
pyometra (1 paper, 2023). "As a granulocyte-macrophage colony-stimulating factor receptor agonist, sargramostim may be stimulating upregulated expression of CSF2RA and CSF2RB and activating mature granulocytes and mononuclear macrophages to improve anti-infection and immune function in canine pyometra." (PMID 37101686, 2023).
sarcoidosis (1 paper, 2025). Sarcoidosis is a multisystemic disorder of unknown cause characterized by the formation of immune granulomas in involved organs. "A heatmap analysis further demonstrated an upregulation of key genes involved in these pathways, particularly in the progressive sarcoidosis group, including CSF2RB, CSF2RA, IL3RA, STAT5A, and STAT1." (PMID 41476976, 2025).
skin cutaneous melanoma (1 paper, 2025). "The TIMER2.0 database mutation module showed that 0.5% of BRCA samples have CSF2RB mutation, while skin cutaneous melanoma (SKCM) showed the highest rate of 11.5% of samples mutated for this gene." (PMID 40837403, 2025).
Stroke (1 paper, 2025). Sudden impairment of blood flow to a part of the brain due to occlusion or rupture of an artery to the brain. "Specifically, PPARα KO led to increased expression levels of Gadd45b, Nppa, Hdc, Lcn2, Il6, Sox4, Marcksl1, Saa3, Ucn2, Met, Dusp10, Elovl7, Ngf, C3, Il11, Hmox1, Alox5, Tnfsf9, Angptl4, Plin2, H19, Csf2rb, Atf3, and Col7a1 following stroke." (PMID 40362325, 2025).
tumor (15 papers, 2016 to 2025). "In contrast, the result obtained from the TIMER2.0 database (hosting only TCGA data) showed that BRCA normal samples had significantly higher expression of CSF2RB than BRCA tumor samples." (PMID 40837403, 2025). "In BRCA, the median expression of the CSF2RB gene is higher in normal samples than in the matched tumor samples." (PMID 40837403, 2025). "CSF2RB expression was found to be downregulated in BRCA tumor samples compared to that in paired normal samples and upregulated in AML compared to that in its normal counterpart." (PMID 40837403, 2025). "Our results showed that at the transcriptional level, Csf2ra (GM-CSFR-α) and Csf2rb (GM-CSFR-βc) are expressed in tumor immune cells." (PMID 40075752, 2025). "As expected, the promoter of the CSF2RB gene is hypermethylated in tumor tissues, and the methylation level is higher than that in normal tissues." (PMID 40837403, 2025). "We analyzed CSF2RB genetic changes, mRNA expression, DNA methylation, prognosis, and immune infiltration levels across different tumor types, with a focus on breast and hematological malignancies." (PMID 40837403, 2025). "Among these genes, SPINT2, LNX1, FOXA2, and SOSTDC1 were reported to be related to tumor progression, whereas TYROBP, TREM2, IL23R, CSF2RB, TRAF1, and TGFBR1 were closely associated with immune response." (PMID 36611170, 2023). "MOLM-13 cells expressing either CSF2RB shRNA or control shRNA were injected subcutaneously into the flanks of Rag2/Il2rg-mutant mice and tumor growth was monitored by caliper measurements." (PMID 34750506, 2022). "Western blot analysis also confirmed the decrease in CSF2RB protein expression in 6 cancerous tissues than in tumor-adjacent tissues." (PMID 35574409, 2022). "It showed that the expression of CSF2RB in tumor tissues was significantly lower than normal tissues, while the expression of CCR2 remained the same in the two different tissues." (PMID 35574409, 2022). "At the same time, we also verified the expression of the CSF2RB gene by using the tumor tissue in our own institute." (PMID 35574409, 2022). "Immune and stromal cell populations included 2 populations: Macrophages 1 (c1: C1qa, C1qb, C3aR1, Cd68, Csf1r, Tlr2, and Cd86) and 2 (c6 + c9: Ccr7, Csf2rb, Il1b, and Cd74) expanded in PNs as a percentage of total tumor cells." (PMID 36134665, 2022). "Finally, we sought to analyze CSF2RB expression across diverse cancer types, including tumor and normal samples of the TCGA program, using the UALCAN database." (PMID 40837403, 2025). "However, in all these results, CSF2RB gene expression is higher in normal than in the tumor tissues in the context of BRCA." (PMID 40837403, 2025). "The expression of CSF2RB in tumor tissues was lower than that in normal tissues." (PMID 35574409, 2022). "We identified that CSF2RB played an important role in the tumor microenvironment of LUAD." (PMID 35574409, 2022). "Moreover, the highest expression of CSF2RB was observed in AML tumor tissue (n = 173)." (PMID 40837403, 2025). "Finally, tumor tissues from LUAD patients were used for the assessment of CSF2RB expression." (PMID 35574409, 2022). "Analysis of CSF2RB gene expression data from the GEPIA cancer database showed its downregulation in BRCA compared to that in paired normal controls (291 normal samples and 1,085 tumor samples)." (PMID 40837403, 2025). "To better understand the role of CSF2RB in the tumor microenvironment of LUAD, first we used the CIBERSORT algorithm to assess the differences of LUAD patients in 22 TIIC subgroups according to the expression level of CSF2RB." (PMID 35574409, 2022). "Immunohistological analysis of paraffin-embedded tumors revealed almost absent phosphorylation of STAT5 in CSF2RB diminished tumor material." (PMID 34750506, 2022).
tumor (continued). "Similarly, the expression of BTN3A1, CSF2RB, GIMAP7, GZMB, HCLS1, LCP2, and SELL was positively correlated with the infiltration of B cells, CD8+ T cells, CD4+ T cells, neutrophil, and DCs, but was negatively correlated with the tumor purity." (PMID 33042828, 2020). "In addition, an up-regulation of macrophage receptors involved in cell activation and recruitment (e.g. CD80, CD86, CSF3R, CSF2RB and CD209) was observed 8 hours after treatment possibly indicating an increased presence of activated macrophages in the tumor at this point in time." (PMID 27463372, 2016).